IGF1 (insulin like growth factor 1)
Diseases named in the same sentence as IGF1 in open-access papers (continued):
Sharing a sentence is not in itself a finding about the gene and the disease.
tumor (continued). "CAFs are a major component of the TME, providing physical support in it and secreting various proteins, such as extracellular matrices (ECMs), hepatocyte growth factor (HGF), insulin-like growth factor 1/2 (ILGF1/2) and cytokines that can modulate tumor growth and survival." (PMID 36835352, 2023). "Disruption of the complex in HNSCC cells in vitro with a peptide mimetic of the organizer site in Sdc1 (called SSTNIGF1R) inactivates IGF1R, even in the presence of IGF1, and relieves the suppression of apoptosis signal-regulating kinase-1 (ASK1), dramatically reducing tumor cell survival." (PMID 36968227, 2023). "Accordingly, the insulin-like growth factor-1 (IGF-1) receptor was shown to be more abundantly expressed in adamantinomatous than in the papillary type of CP, an observation that possibly implicates the IGF-1 receptor in the recurrence of this type of tumor." (PMID 37174978, 2023). "The invasiveness of tumor and levels of blood prolactin are independent factors for LTLs before surgery, whereas GH and IGF-1 levels are not." (PMID 37886642, 2023). "However, our previous results showed that UCMSCS&XFM−CD expressed high levels of PDGF and IGF-1, and it has been found that these cytokines enhance MSC-mediated tumor promotion." (PMID 38087382, 2023). "The lower level of IGF-1 in PDAC could be explained by the impact of GH stimulation, liver production, or tumor synthesis." (PMID 37373743, 2023). "The IGF system plays an important role in estrogen-induced EC and high IGF1 levels stimulate proliferation, migration as well as invasion, and thus promote tumor growth, angiogenesis and metastasis." (PMID 37313172, 2023). "Upregulation of procancer genes (Spp1, Igf1, Plgs2, Plau, Ctsk, Areg, Hbegf, Il1a, Ilb) was found in TAM-WT compared with TAM-KO, and this aligns with the observation that CL-11 is required for tumor cell proliferation, tumor growth, and angiogenesis." (PMID 36883567, 2023). "Here we demonstrate that administration of DMBA induced increased expression of IGF-1, IGF-1R, pIRS, and ER in the tumor tissues of obese rats with subsequent activation of downstream molecules in the signaling pathway that could promote tumor development." (PMID 37511200, 2023). "Directly after tumor resection, IGF-1- and GH-levels have already decreased (GH: 4 ng/ml; IGF-1: 237 ng/ml) and were finally normal nine months after surgery (GH: 1 ng/ml; IGF-1: 215 ng/ml)." (PMID 36508085, 2023). "GH2h also showed a positive correlation with basal GH (rs 0.60; p<0.001), maximal tumor diameter (rs 0.37; p=0.01), and tumor volume (rs 0.33; p=0.03), but not with baseline IGF1 (rs 0.17; p=0.26)." (PMID 38027102, 2023). "Moreover, serum tumor markers BALP, IGF-1, and SAA were reduced in both cohorts after two weeks of chemotherapy drug withdrawal, with lower levels in CMG." (PMID 36880008, 2023). "IGF-1 signaling thus couples the induction of mitochondrial biogenesis to basal levels of mitochondrial turnover via Nrf2 and BNIP3, thereby maintaining mitochondrial homeostasis and facilitating tumor progression." (PMID 36835075, 2023). "The reduction of IGF-1 in response to caloric restriction inhibits the PI3K-AKT-mTOR pathway and thus reduces the proliferation of tumor cells, immunosuppressive Tregs, and collagen deposition in TME and promotes normalization of tumor vasculature." (PMID 37568713, 2023). "Additionally, insulin promotes cell proliferation and increased insulin, in addition to insulin-like growth factor 1 (IGF1) and IGF2 levels, critically stimulates tumour initiation and progression in insulin-resistant patients." (PMID 37761999, 2023). "It should be mentioned that beyond Ins, IR may act as a receptor for both Insulin-like Growth Factor (IGF)-1 (IGF-1) and IGF-2, which themselves prompt tumor-promoting responses." (PMID 37461077, 2023).
tumor (continued). "These infiltrated immune cells and solid tumor cells release tumor-progressing cytokines (IL-6, TNF-α, TGF-β), chemokines (CCL2, CCL5, CCL18, CXCL8, CXCL12), and growth factors (EGF, PGF, IGF-1, IGF-2, PDGF) that promote tumor microenvironment immunosuppressive." (PMID 37371075, 2023). "Invasiveness of the tumor and the level of blood prolactin are independent factors for LTLs before surgery, whereas the GH and IGF-1 levels are not." (PMID 37886642, 2023). "Our study found that the level of IGF-1 was significantly higher in patients with recurrence, while there was a significant reduction in patients who completed trastuzumab therapy without tumor recurrence." (PMID 38406785, 2023). "Additionally, IGF1 and IGF2, which activate PI3K signalling in tumours in an autocrine manner, were also significantly upregulated in MPT tumours compared to IDC." (PMID 36522480, 2023). "Further, the liver synthesized growth factors IGF-1 and HGF/SF are affected by levels of exercise, stress, nutrition and BMI, and may contribute to metastatic progression and tumor cell homing to the liver." (PMID 36973672, 2023). "Given the proven role of IGF/IGF1R in fibroids proliferation, our data suggest that IGF1 may activate ERα in a ligand-independent manner, promoting tumor cell proliferation." (PMID 35884847, 2022). "However, we found that both PAPPA and IGF1 were predominantly expressed in the stroma of ILC, while IGF1R was expressed within the tumor epithelium." (PMID 35205651, 2022). "Various molecules originated from CAFs and tumor-infiltrating immune cells such as TGF-β, FGF, EGF, HGF, and IGF1 along with Hedgehog, Notch, and Wnt signaling pathways could promote EMT." (PMID 35769483, 2022). "Arguing against a specific role for IGF-1 is a prior report that liver-specific deletion of Igf1 in TRAMP mice did not impact tumor progression." (PMID 35741020, 2022). "IGF-1/IGF-1R axis contributes to the proliferation and invasion of tumor cells." (PMID 36003786, 2022). "In addition, there was a strong statistically significant positive correlation between CRF and glucose level (ρs = 0.623), and a moderate positive correlation between CRF and tumor size (ρs = 0.573) and CRF and IGF-1 (ρs = 0.548)." (PMID 36431227, 2022). "IGF1 and GAS6 act as paracrine-reciprocal signals for activating the receptor tyrosine kinases IGF1R and AXL (“anexelenko”, which means “uncontrolled” in Greek), respectively, in tumor cells." (PMID 35159011, 2022). "The activation of the IGF-1/IGF-1R signaling pathway may activate the MAPK and PI3K signaling pathways that are closely related to tumor genesis, resulting in the occurrence of tumor." (PMID 36003786, 2022). "After 7 months, lanreotide failed to decrease IGF-1 concentrations by > 20% or induce tumor shrinkage (tumor volume change of < 25%) and he underwent a second surgical procedure via the transcranial route." (PMID 35090028, 2022). "Indeed, in vitro studies have shown that these proteins can have a tumor suppressive effect on IGF activity by sequestering circulating IGF-1 and IGF-2, thereby reducing their binding to IGF-1-2Rs." (PMID 35162142, 2022). "Importantly, serum IGF1 levels were significantly suppressed due to GHRA, in the tumor bearing mice." (PMID 35865483, 2022). "Exposing LNCaP to IGF-1 did not result in a significant alteration of tumor growth, whereas a significant increase in VCaP cells was seen after 72 h IGF-1 incubation." (PMID 35053528, 2022). "Adhesion of DU145, but not PC3, was diminished significantly when the tumor cells were shortly pre-incubated with IGF-1 for 4 h." (PMID 35053528, 2022).
tumor (continued). "These compounds are structurally very similar to IGF-1 and bind competitively to IGF-1R, suppressing its auto-phosphorylation to silence its signaling and, thereby, preventing the growth and progression of tumor tissue." (PMID 36009569, 2022). "Correspondingly, the tumor weights of Cis-participated groups were dramatically lower than those of the model group; FJD addition enhanced the antitumor effect of Cis, the same as LY, while IGF-1 partially reversed this antitumor effect." (PMID 35281608, 2022). "Since we found high mRNA expression levels of IGF1R in tumor cells, we wanted to understand whether IGF1R/IGF1 axis plays a role in cell migration." (PMID 35574343, 2022). "Some studies have suggested that the anabolic process of IGF-1 and IGFBP1 may make use of substrates such as amino acids to promote tumor development." (PMID 35903696, 2022). "Contrasting with its putative tumor suppressor role through IGF-2, H19 may also have an oncogenic role through IGF-1 regulation." (PMID 35597813, 2022). "Furthermore, BMSCs release IL-6 and IGF-1, which activate the signal transduction pathways that mediate drug resistance and increase the activation of HIF-1, affecting tumor metabolism and drug resistance." (PMID 36362718, 2022). "Consequently, alterations in IGF-1 and IGFBP-1 levels affect the balance between cell proliferation and apoptosis, finally leading to tumor development." (PMID 34205356, 2021). "Notably, since EWS tumor cells express both IGF-IR and IGF-1, an autocrine loop enhances EWS progression." (PMID 34069554, 2021). "Moreover, tumor cells can produce hybrid forms of insulin and IGF-1 receptors that can either be activated by insulin, IGF-1, and/or IGF-2." (PMID 33920079, 2021). "An interesting possibility would be to look for variants of EGF, HGF, IGF-1, and VEGF as has already been done with other molecules; this would foster the regeneration process or at least not hinder it, without affecting tumor progression." (PMID 34572344, 2021). "Importantly, knockdown of GPER or HIF-1α abolished the observed IGF1-induced upregulation of VEGF, further demonstrating the contribution of GPER in a CAF-induced angiogenic tumor microenvironment." (PMID 33802978, 2021). "Moreover, the expression of IGF-1 and KCC in surgical specimens shows an excellent linear correlation to tumor size, the in vivo indicator of tumor progression." (PMID 35008759, 2021). "Elevated insulin can also increase free IGF-1 (i.e., the bioactive form of IGF-1) in the blood by reducing the production of IGF-1-binding proteins 1 and 2 in the liver, thereby positively enhancing tumor development." (PMID 34831299, 2021). "Moreover, IL-4, through activation of NFAT and STAT6 transcription factors, induces the expression of IGF-1 in TAMs, which signals neighboring tumor cells to activate the PI3K pathway to promote cell proliferation and tumor expansion." (PMID 34949203, 2021). "Given the increased levels of IGF-1 and the strongly activated PI3K/Akt-mTOR pathway observed in OS, CR could potentially be effective against this tumor." (PMID 34715874, 2021). "PAK phosphorylation was considerably elevated when tumor cells were triggered by combinations of SDF-1a, IGF-1, and HGF which could play an effective role in promoting myeloma cell migration to the large extent." (PMID 33768092, 2021). "Moreover, the inhibition of EWS-FLI1 fusion protein decreased IGF-1 and impaired the IGF-1/IGF-1R signaling correlated with increased EWS cell apoptosis, reduced migration, and repressed tumor xenograft growth in a mouse model." (PMID 34069554, 2021). "Besides, fibroblasts in the NPC microenvironment can secrete varied growth factors, including EGF, FGF, IGF1, CSF and TGF-β, which can either facilitate tumor progression or immune suppression." (PMID 34568077, 2021). "Furthermore, high expression level of IGF-1 and IGF-1R were closely connected with high degrees of tumor infiltrates, including CD4+ T cell, dendritic cells, and macrophages." (PMID 34804946, 2021).
tumor (continued). "Moreover, the study observed that expression levels of ERK, IGF-1, and GLUT4 were correlated with CRC clinical characteristics, such as tumor size, distant metastasis, and advanced stages (III/IV)." (PMID 34638601, 2021). "Unlike caloric restriction, protein restriction results in a conserved decrease in insulin‐like growth factor (IGF)‐1 levels and the activity of the IGF‐1/akt/mechanistic target of rapamycin complex 1 (mTORC1) pathway leading to a decrease in tumor growth." (PMID 33675103, 2021). "IGF-1 interactions with its cognate receptor IGF-1R on the surface of tumor cells and phosphatidylinositol 3-kinase (PI3K) signaling pathway activation resulted in tumor resistance and proliferation." (PMID 33766119, 2021). "Treatment response was superior to that in the SGST group: the reduction in IGF1 was in the range 20%‐50% in 2 patients (SLT and DGST), in 6 patients (3 DGST and 3 SLT) the reduction was by more than 50%, and in 6 patients the IGF1 level was fully normalized (5 SLT and 1 plurihormonal tumour)." (PMID 33491286, 2021). "Mice bearing IGF-1- and IGF-2-overexpressing MCF-7L cells had earlier onset of tumorigenesis and increased tumor growth rate compared with mice bearing control MCF-7L cells, which is probably due to increased amino acid synthesis under the regulation of IGF signaling." (PMID 33429867, 2021). "Compared to control HF group, LC and HC alone were not sufficient to reduce tumor growth in obese mice, despite the lower body weight and lower levels of IGF-1 and leptin in the HC group." (PMID 31906264, 2020). "Targeting the IGF1 and IGFBP3 signaling pathway may strengthen GO-related cytotoxicity with the potential to increase the survival of patients affected by this tumor." (PMID 32742448, 2020). "PCR array demonstrated that inhibiting RCC2 expression significantly decreased the expression of IGF1 and TWIST1, two well-known tumor-enhancing genes, in MCF-7 cells; conversely, overexpressing RCC2 increased the expression levels of these two genes in the transfected cells." (PMID 32565805, 2020). "IGF-1R binding with either IGF-1 or IGF-2 will undergo receptor autophosphorylation and cross-linking, and then the signals activate both PI3K/Akt/mTOR and Ras/Raf/MEK/ERK pathways to enhance tumor progression." (PMID 32498447, 2020). "These cells establish a favorable environment for tumor development by releasing cytokines (IL-6, IL-10 and TGF-β), metalloproteinases (MMP3 and MMP9) and growth factors (HGF, EGF, CTGF and IGF-1), leading to immunomodulation, angiogenesis, invasion, proliferation and tumor cell survival." (PMID 32899449, 2020). "Tumor angiogenesis is significantly enhanced in obese state, mainly due to the elevated circulating pro-angiogenic/-inflammatory factors released from adipocytes, such as VEGF, IGF-1, MCP-1, IL-1, TNF, etc24." (PMID 31996731, 2020). "There are also results of studies on diethylnitrozamine-induced HCC in mature mice, in which a lowered expression of mRNA of two isoforms (local MGF and endocrine form of IGF1) in HCC, as well as increased expression in tissue surrounding the tumor, compared to control tissues, was described." (PMID 32977489, 2020). "They assessed circulating interleukin-6 (IL-6), VEGF, fasting insulin, and tumor expression of insulin-like growth factor-1 receptor (IGF-1R), insulin receptor (IR), insulin-like growth factor-1 (IGF-1), and RAGE markers before surgery and 6 months after tumor surgery." (PMID 33117687, 2020). "Other tumor biomarkers have been proposed such as osteopontin (OPN), vascular endothelial growth factor (VEGF), angiopoietin 2 (ANG-2), Golgi protein 73 (Gp-73), insulin growth factor-1 (IGF-1), hepatic growth factor (HGF), Glypican-3 and c-MET among others." (PMID 32492896, 2020). "Complete response to surgery was defined as normalization of IGF-1 levels without evidence of residual tumor at the time of last follow-up." (PMID 32843993, 2020).
tumor (continued). "It indicated that the COL1A1, IGF1, COL5A1, CXCL12, PTEN, and SPP1 were significantly differently expressed in EC tumor compared with those in normal samples (P = 4.93E−02, P = 5.24E−03, P = 2.83E−04, P = 1.58E−06, P = 2.11E−12, and P = 6.91E−13, respectively)." (PMID 32641130, 2020). "IGF-1 signals intracellularly through the PI3 and MAPK pathways after binding to IGF-1R on the cell surface, and IGF-1 thereby increases the enzymatic activity of MMP-2 and MMP-9 and enhances the proliferation and migration of tumor cells." (PMID 32972437, 2020). "Whereas, regarding non-overweight patients, IGF-1 level (P = 0.005), tumor size (P = 0.040), and nodal status (P < 0.001) were correlated with OS in univariate models." (PMID 32391265, 2020). "Through rescue assays, we confirmed that IGF-1, the activator of PI3K/AKT/mTOR pathway, could counteract the suppressive influence of ZEB1-AS1 silence on tumor growth and development of TC." (PMID 32231464, 2020). "Support for this notion came from the observation that the MEK inhibitor U0126 attenuates hepatocyte growth factor-induced proliferation in human granulosa-like tumor cell line (KGN cells) and insulin-like growth factor 1-induced, AKT-mediated proliferation in human luteinized granulosa cells." (PMID 31915051, 2020). "Additionally, mice fed a low-fat diet show significantly lower levels of serum prostate-specific antigen (PSA), serum insulin, and tumor Igf1 mRNA levels relative to HFD mice, as well as a slower tumor-growth rate in LAPC4 xenografts." (PMID 32093338, 2020). "In a study including 20 patients (six newly diagnosed and 14 relapsed disease), IGF-1 levels decreased significantly with octreotide (250 μg/day), but tumor burden did not change." (PMID 32121432, 2020). "While their levels generally increase after resistance exercise in human, IGF-1 and TGF-β1 have been shown to be regulated by voluntary or forced swimming in mice, initiated whether before or after tumor inoculation." (PMID 31936342, 2020). "Protein kinase C activation can reduce tumor growth of CRC cells, and protein kinase C beta II could inhibit CRC by modulating IGF-1-mediated cell survival." (PMID 30446877, 2019). "As in the case of insulin and IR, the expression of the ligand (IGF1) and its receptor (IGF1R) within the same tumor could provide proof of an autocrine-paracrine signaling loop of RCC cells stimulation." (PMID 30929166, 2019). "In male but not female mice in which IGF1 production in the liver is downregulated at adult ages, lifespan is decreased and tumor incidence is increased." (PMID 30981207, 2019). "Indeed, experimental data suggest that IGFBPs sequester circulating IGF-1 and IGF-2, thus limiting their IGF-IR interaction and exerting a tumor suppressor activity." (PMID 31269742, 2019). "However, more than 50% GBM patients suffer from recurrence, which is derived from elevated secretion of insulin-like growth factor-1 (IGF-1) from TAMs and IGF-1 induced elevation of phosphatidylinositol 3-kinase (PI3K) pathway signaling in GBM tumor cells." (PMID 34322663, 2019). "The IL-6-STAT3 mediated IGF-1/IGF-1R signaling or DNMT3b-OCT4-DNMT1 regulation in HCC may be two of the multiple factors involved in stemness expression and tumor recurrence." (PMID 31771617, 2019). "The IGF1/IGF1R system may also influence cancer progression due to promoting adhesion and migration of cells, as well as angiogenesis within tumor tissues and in the surrounding areas." (PMID 31293513, 2019). "Early (1 to 4 months) symptom control was observed, with an absence of tumor growth and normalization of IGF-1 levels in all patients." (PMID 31365626, 2019).